CYP7A1 (cytochrome P450 family 7 subfamily A member 1)
Diseases named in the same sentence as CYP7A1 in open-access papers (continued):
Sharing a sentence is not in itself a finding about the gene and the disease.
Obesity (continued). "Therefore, CYP7A1, a key regulator in the cholesterol synthesis pathway, plays an important role in controlling cholesterol bile acid synthesis and inhibiting development of obesity." (PMID 31450828, 2019). "This indicates that obesity triggers the activation of the FXR/FGF15 signaling pathway in the rat small intestine, which coincides with a pronounced decrease in hepatic CYP7A1 levels (P < 0.01)." (PMID 39758340, 2024). "Transgenic mice overexpressing CYP7A1 have an expanded BA pool and are resistant to HFD-induced obesity, fatty liver, and insulin resistance." (PMID 35614477, 2022). "In this study, MOP supplementation increased Cyp7a1 and Cyp7b1 expression in the liver compared to the HFD group, suggesting that MOP may prevent obesity by regulating bile acid metabolism." (PMID 35548566, 2022). "However, mice treated with an intestinal FXR inhibitor and transgenic mice overexpressing CYP7a1 had increased BA pool size and energy expenditure, and were thus were highly resistant to HFD-induced obesity." (PMID 34973477, 2022). "Furthermore, the Cyp7a1 transgenic mice were resistant to HFD-induced insulin resistance and obesity." (PMID 36211528, 2022). "It is plausible that the obesity and subsequent NAFLD in our mice may have inhibited the upregulation of LXR and CYP7A1 activities." (PMID 24672716, 2014).
hyperlipidemia (37 papers, 2009 to 2025). "Moreover, although the functional role of the CYP7A1 gene in humans has been reported, particularly its deficiency in hyperlipidemia, the generalizability of our findings to humans needs further investigation." (PMID 39968496, 2025). "Moreover, a genetic deficiency of Cyp7a1 in humans results in hyperlipidemia." (PMID 21762485, 2011). "In our study, FXR in the intestine was extremely reduced in hyperlipidemia rats, which would relieve the inhibition of CYP7A1 and thus produce more primary bile acids in liver." (PMID 33679408, 2021). "It was found that AEE inhibited FXR expression and upregulated CYP7A1, which was beneficial for hyperlipidemia treatment through facilitating the conversion of cholesterol into BAs." (PMID 34899293, 2021). "In this study we observed that gypenosides decreased the hepatic gene expression levels of Shp in hyperlipidemia mice while they increased the gene expressions of Cyp7a1 and Lrh1." (PMID 30105069, 2018). "Our previous studies have shown that FTZ effectively alleviates hyperglycemia and reduces hyperlipidemia by the regulation of cytochrome P450 family 7 subfamily A member 1 (CYP7A1), cytochrome P450 family 7 subfamily A member 1 (HMG-CoA), and insulin receptor substrate 1 (IRS1-GLUT2)." (PMID 35784533, 2022). "Similarly, resveratrol significantly reduced FXR mRNA and protein levels, inhibited activation of the FXR/FGF15 axis, increased CYP7A1 mRNA and protein levels, and improved hyperlipidemia." (PMID 35257010, 2022). "Among six candidate targets (Srebp-1c, Cyp7a1, Cyp3a9, Pcsk9, Insr, and Gck), Srebp-1c and Insr may play central role in the treatment of hyperlipidemia." (PMID 33936248, 2021). "In addition, proprotein convertase subtilisin/kexin type 9 (Pcsk9) and cholesterol 7α-hydroxylase (Cyp7a1) were the key genes both enriched in the cholesterol metabolism pathways in hyperlipidemia rats treated with HTJZD." (PMID 33936248, 2021). "Therefore, we speculated that AEE probably affected the metabolism of bile acids by regulating the gut microbiota, resulting in the down-regulation of FXR expression and up-regulation of CYP7A1 expression to alleviate hyperlipidemia in the body." (PMID 36618709, 2022). "Cholesterol 7α-hydroxylase (CYP7A1), the rate-limiting enzyme in the classical bile acid synthesis pathway, is a promising target for hyperlipidemia therapy." (PMID 40807276, 2025). "Cytochrome P450 family 7 subfamily A member 1 (CYP7A1) and 3-hydroxy-3-methylglutaryl-CoA reductase (HMGCR) are key antioxidant enzymes that show differential expression in hyperlipidemia." (PMID 36539694, 2022). "The results showed that ST improved the anti-hyperlipidemia effects of CDCA, and increased mRNA and protein expression of FXR and CYP7A1 in the liver." (PMID 36030278, 2022). "The results of the current study are consistent with reports indicating that hepatic CYP7A1 and CYP8B1 expression are lowered in diet-induced hyperlipidemia models and that FGF15/19 suppressed expression of both these genes." (PMID 33036208, 2020). "In hyperlipidemia model, IOP‐A2 hypolipidemic role seems to occur mainly by promoting cholesterol metabolism and regulating the expression of the cholesterol metabolism‐related proteins CYP7A1, LXRα, SR‐B1, and ABCA1." (PMID 38628208, 2024). "CYP7A1 and HMGCR mediate the conversion from cholesterol to bile acid in the liver and thus have become potential drug targets to induce lipid-lowering effects in hyperlipidemia." (PMID 36539694, 2022).
hyperlipidemia (continued). "Through the JNK/C-Jun/CYP7A1 pathway, puerarin efficiently decreases the phosphorylation level of JNK in mouse livers produced by carbon tetrachloride, contributing to the reduction of oxidative stress and hyperlipidemia." (PMID 36432411, 2022). "Therefore, taken together, these results revealed that AEE ameliorated hyperlipidemia via regulating liver and fecal metabolomics profiles, FXR-mediated upregulating of CYP7A1, and upregulating G-BA levels and downregulating T-BA levels." (PMID 34899293, 2021). "In conclusion, this study found that AEE decreased FXR and increased CYP7A1 in the liver, which might be the possible molecular mechanisms and targets of AEE for anti-hyperlipidemia therapies." (PMID 34899293, 2021). "Due to the significant effect of WWQZS for lowering cholesterol in pharmacology experiments above, the protein expression of HMGCR, CYP7A1, p-AMPKα, and p-ACC for cholesterol metabolism was evaluated in livers of WWQZS-treated hyperlipidemia hamsters by Western blotting." (PMID 32454862, 2020). "The results showed that L. plantarum FZU3013 prevented NAFLD and hyperlipidemia by modulating specific intestinal microbial phylotypes and increasing the expression levels of genes relating to lipid metabolism, including the bile salt export pump (BSEP) and cholesterol 7α-hydroxylase (CYP7A1)." (PMID 36698477, 2022). "Hence, AEE might promote the production of hepatic BAs via feedback mechanism by CYP7A1, resulting increased fecal TBA excretion, which could make contribution to the improvement effects of AEE on hyperlipidemia." (PMID 34899293, 2021). "Our results showed that Dp3-Sam treatment increased the CYP7A1, CPT1, ACOX, and PPARα expression in the liver tissue of HFD rats, indicating that Dp3-Sam intervention inhibited lipid accumulation via acceleration of lipid oxidation in HFD-induced hyperlipidemia rats." (PMID 34281481, 2021). "After the administration of the IOP‐A, the CYP7A1 expression in the hepatic tissue increased and the expression of SREBP‐1C protein decreased significantly, indicating that the IOP‐A may promote the metabolism of cholesterol by activating CYP7A1 and inhibiting SREBP‐1C in hyperlipidemia rats." (PMID 36655098, 2023).
Hepatic steatosis (34 papers, 2014 to 2025). Steatosis is a term used to denote lipid accumulation within hepatocytes. "For the first time, we also show that the knockout of hepatic Cyp7a1 reduced bile acid content but increased hepatic steatosis and that it negated the capacity of exercise to lower hepatic steatosis induced by a chronic HFD." (PMID 40194946, 2025). "We then studied the effects of reduced bile acid synthesis on metabolism using Cyp7a1-knockout mice to test if these animals were more prone to developing fatty liver and diabetes on a high-fat and high-cholesterol diet." (PMID 37019215, 2023). "For example, genetic overexpression of Cyp7a1 in mice results in a protection against diet‐induced hepatic steatosis paired with greater fecal excretion of BA and altered BA composition." (PMID 35923133, 2022). "There is growing interest in understanding the role of BA metabolism in chronic disease with a specific interest in Cyp7a1, the rate‐limiting enzyme for BA synthesis, as a potential target for therapeutic interventions to prevent hepatic steatosis." (PMID 35923133, 2022). "Our data showed that fucoidan significantly reversed the ethanol-induced reduction of ileac FXR and FGF15 levels and decreased CYP7A1 levels in hepatic tissues to relieve liver steatosis." (PMID 33994911, 2021). "Several studies have shown that deletion of Cyp7a1 led to hepatic steatosis, oxidative stress, apoptosis and fibrosis." (PMID 30405201, 2018). "miR-17 is a novel regulator of CYP7A1 signaling in hepatic lipid metabolism, suggesting a potential therapeutic approach for fatty liver." (PMID 29721023, 2018). "While Cyp7a1-deficient mice from birth exhibit protection from metabolic disorders without altering hepatic steatosis on an HFD." (PMID 40194946, 2025). "It positively correlates with plasma levels of bile acids and hepatic mRNA expression of cholesterol 7 alpha-hydroxylase (CYP7A1) in mice, which trigger hepatic lipogenesis and hepatic steatosis via the bile acid-mediated hepatic farnesoid X receptor (FXR) signaling pathway." (PMID 37111261, 2023). "Our results above indicate that miR-17 induced the development of fatty liver and these effects could partially be attributed to the mediation of CYP7A1." (PMID 29721023, 2018). "However, the relationship between Cyp7a1 and hepatic steatosis is complex." (PMID 40194946, 2025). "CYP7A1 is a key enzyme in bile acid synthesis from cholesterol and therefore the decreased expression of HNF4α and CYP7A1 reduce bile acid synthesis and flow, and may contribute to the development of hepatic steatosis." (PMID 38478087, 2024). "Therefore, suppression of Cyp7a1 leading to hepatic cholesterol accumulation may be a novel mechanism of high-fructose diet-induced fatty liver." (PMID 24551121, 2014). "Mechanistic investigations revealed that ILA upregulated hepatic CYP7A1 and FXR-BSEP expression, stimulating hepatic bile acid biosynthesis and biliary excretion to alleviate liver steatosis." (PMID 40860180, 2025). "In contrast, in this study, the inducible liver-specific Cyp7a1 knockout model displayed normal weight on the HFD compared to controls and developed increased hepatic steatosis in both sexes." (PMID 40194946, 2025). "This reduces hydrophobic secondary bile acids such as DCA/LCA, restores CYP7A1 negative feedback, and consequently ameliorates hepatic steatosis and colonic motility." (PMID 41465567, 2025). "In regard to hepatic steatosis, Hyp attenuated the lipid accumulation in liver by preserving hepatic lipid and bile acid homeostasis via the regulation of PPARγ, FXR, LXRα, ACC, SREBP, cholesterol 7α-hydroxylase (CYP7A1), and CYP27A1." (PMID 35892639, 2022). "CYP7A1 is important in cholesterol catabolism and the prevention of HFD-induced fatty liver." (PMID 35614477, 2022).
Hepatic steatosis (continued). "Another study reported that LBP upregulates key enzymes, such as CYP7A1 and CYP8B1, activates FXR and SHP, and downregulates the FGFR4–β-Klotho complex, thereby reducing its inhibitory effect on CYP7A1 and enhancing bile acid synthesis in mouse models of hepatic steatosis and hypertriglyceridemia." (PMID 41480362, 2025). "In a diet-induced steatosis model, CH25H has been reported to positively regulate CYP7A1 and CYP27A1 and reduce small heterodimer partner (SHP), thus increasing the synthesis and excretion of BAs, drastically reducing the high-fat diet-induced hepatic steatosis." (PMID 39287458, 2024). "Considering our previous findings demonstrating HCR rats are protected against HFHS‐induced hepatic steatosis and our current study demonstrating HCR rats have greater Cyp7a1 expression in response to HFHS, we hypothesized HCR rats would exhibit greater fecal BA in response to acute HFHS." (PMID 35923133, 2022). "Treatment with the clinical candidate, obeticholic acid reversed the hepatic steatosis phenotype and transcriptomic analysis confirmed the selective activation of FXR target genes including upregulation of FGF19 and PLIN1 and downregulation of SLC51B and CYP7A1 genes by OCA." (PMID 33334026, 2020).
dyslipidemia (30 papers, 2013 to 2026). "In summary, our study demonstrated that five polymorphisms situated in the promoter and enhancer regions of the CYP7A1 gene are associated with the risk of ACS and higher incidences of dyslipidemia and T2DM in Mexican patients with ACS." (PMID 38540230, 2024). "The increased content of CYP7A1, converting cholesterol to bile acids for the excretion, suggests that cholesterol catabolism is another important mechanism to improve the dyslipidemia." (PMID 36234935, 2022). "In contrast, HFD+CHOL caused macrovesicular steatosis, inflammation, early fibrosis, atherogenic dyslipidemia, intrahepatic cholesterol accumulation, hepatocyte apoptosis, upregulated Srebf1, Cyp7a1, and Nfkb1 expression, and activated Nrf2-dependent antioxidant responses." (PMID 42196216, 2026). "Dyslipidemia might be explained by an increase in hepatic mRNA expression of Cyp7a1 and fatty acid synthase, while lipid efflux of PHD3dko macrophages was comparable to controls." (PMID 34055796, 2021). "SLKDT downregulated PPAR‐γ and C/EBP‐α mRNA expressions and upregulated PPAR‐α, CPT‐1, LPL, and CYP7A1 mRNA expressions to reduce adipocyte differentiation and fat accumulation, accelerate fat oxidation, and improve dyslipidemia, then inhibit the immune response and alleviate liver injury." (PMID 32884731, 2020). "This promotes the expression of cholesterol 7α-hydroxylase (CYP7A1) to accelerate cholesterol metabolism and decrease the serum levels of TC, TG, and LDL-C to improve dyslipidemia." (PMID 40862134, 2025). "After carrying out NR5A2 knockout or overexpression experiments, it was found that NR5A2 reduced the level of inflammation through CYP7A1/CYP8B1, and C/EBPβ-FASN-SCD1 reduced the level of apoptosis, thereby improving the metabolic syndrome." (PMID 37053002, 2023). "Western blot analysis showed that NR5A2, CYP7A1, and CYP8B1 were lowly expressed in metabolic syndrome, and their expression levels were up-regulated after exercise (P < 0.05)." (PMID 37053002, 2023). "SLKDT extracts upregulated mRNA expressions of PPAR‐α, LPL, CPT1, and CYP7A1 and downregulated mRNA expressions of PPAR‐γ and C/EBP‐α, which reduced adipocyte differentiation and fat accumulation, promoted fat oxidation, and improved dyslipidemia." (PMID 32884731, 2020). "In summary, the rat dyslipidemia induced by CSC exposure may be related to the interference of gut microbiota structure and interaction of miRNAs from serum exosomes with target mRNAs, which further regulated AMPK-ACC/CYP7A1 signaling in rats." (PMID 36348421, 2022). "Therefore, SREBP1c, FAS, PPARα, LXR, CYP7A1, and ABCA1 mRNA expression levels were evaluated in our study to investigate whether green tea leaf powder could influence the dyslipidemia in HFD-fed mice." (PMID 33281537, 2020). "FXR-SHP inhibits SREBP-1c, and the activation of FXR-SHP/CYP7A1 facilitated the efflux of lipids by downregulating the SREBP-1c/FAS/ACC pathway and suppressing its downstream target genes, which are involved in fatty acid synthesis, thereby alleviating the progression of dyslipidemia." (PMID 33376498, 2020). "A natural product, such as GSPE, that can induce Cyp7a1 gene expression, inhibit uptake of BAs produced in the process, and reduce lipogenesis may be valuable as a potential combinational therapy with CHY for the treatment of dyslipidemia." (PMID 27111442, 2016).
steatosis (29 papers, 2007 to 2026). Increased lipid within the cytoplasm of cells. "Our previous steatosis adverse outcome pathway-based analysis of the same dataset revealed that Cyp7a1 decreased specifically in males; however, the metabolic network analysis in this study predicted that females also showed a decrease in bile acid metabolism." (PMID 40863960, 2025). "Elevated bile acid synthesis, driven by Cyp7a1, appears critical for the beneficial effects of exercise to treat steatosis induced by an HFD." (PMID 40194946, 2025). "Modulated the expression of specific gene related to lipid synthesis and conversion, CYP4A1, ACC, TNF-α, SOCS2 and CYP7A1; reduced hepatocyte steatosis and liver cell injury." (PMID 36671814, 2023). "Consistent with our findings, hepatic expression of CYP7A1 is known to be significantly elevated in steatosis and NASH patients." (PMID 33324350, 2020). "The marked net loss in liver fat by FGF19 and NGM282 is likely mediated by the FGFR1c-βKlotho and FGFR4-βKlotho receptor complexes, as an agonistic antibody against FGFR1c-βKlotho reduces steatosis and a compound upregulating CYP7A1 increases steatosis." (PMID 30679232, 2019). "The steatosis induction assay showed that transfection with CYP7A1 siRNA can promote HepG2 steatosis compared with the impact on cells transfected with control oligos." (PMID 29721023, 2018). "HepG2 cells stably transfected with miR-17 were transiently transfected with CYP7A1 expression constructs and a control vector for the steatosis assay." (PMID 29721023, 2018). "CYP7A1 was found to participate in miR-17-induced steatosis, as its repressed expression in miR-17 HepG2 cells exacerbated steatotic change." (PMID 29721023, 2018). "To corroborate that CYP7A1 can contribute to cell steatosis, we generated two small interfering RNA (siRNA) constructs targeting CYP7A1." (PMID 29721023, 2018). "When HepG2 cells were transfected with the CYP7A1 expression construct after miR-17 overexpression, a significant decrease in steatosis was observed compared with the control vector." (PMID 29721023, 2018). "Taken together, these results suggest that steatosis promotes bile salt synthesis by dysregulating CYP7A1." (PMID 27535001, 2016). "Consequently, the recovery of normal CYP7A1 levels in the TX mice under TDMQ20 treatment is consistent with both the reduction in steatosis in the liver and the activation of bile excretion of Cu that we recently reported in TX mice treated with TDMQ20." (PMID 41012571, 2025). "Despite that regulation of CYP7A1 is different in human and mice, there is robust evidence that CYP7A1 activation is protective against liver cholesterol accumulation (steatosis), inflammation, and fibrosis." (PMID 35559268, 2022). "Re-introduction of CYP7A1 into miR-17 HepG2 cell partially alleviated steatosis." (PMID 29721023, 2018). "Furthermore, piglets on the astaxanthin regimen exhibited a decline in NR1H3 expression—a gene whose inhibition can foster recovery from hepatocyte steatosis, and increased expression of CYP7A1—a pivotal gene for expelling surplus liver cholesterol through bile acids." (PMID 37893992, 2023). "The study suggested that the Liver X Receptor (LXR) was the primary factor contributing significantly to the combined effect on steatosis, since synergistic effects were evidenced only on LXR target genes, namely Cyp7a1 and Cd36." (PMID 38891072, 2024). "Improved abnormal serum biochemical indicators TG, TC, LDL-C and glucose, inhibited lipid accumulation and steatosis; downregulated CD36 and SREBP-1C, upregulated CYP7A1." (PMID 36671814, 2023). "Eventually, we determined 10 hub genes (Down-regulated genes: MYC, TGFB3, ADAMTS1, THBS1, RASD1, PCDH20; Up-regulated genes: MAMDC4, CYP7A1, GINS2, and PDLIM3) related to NAS and steatosis." (PMID 34777484, 2021).